BTK (Bruton tyrosine kinase)
Diseases named in the same sentence as BTK in open-access papers (continued):
Sharing a sentence is not in itself a finding about the gene and the disease.
Hypertension (22 papers, 2020 to 2025). The presence of chronic increased pressure in the systemic arterial system. "Similar to the earlier generation BTK inhibitors, acalabrutinib has also been reported to cause AF, hypertension, and VA." (PMID 40346640, 2025). "Although no single class of antihypertensive agent has been associated with the prevention or control of BTK inhibitor-related hypertension, the initiation of any antihypertensive agent was associated with a lower risk of MACE." (PMID 37185435, 2023). "Given its high frequency, late onset, and association with MACE, hypertension requires vigilant monitoring throughout the course of BTK inhibitor treatment." (PMID 37185435, 2023). "This may be particularly relevant for managing hypertension, a known contributor to major adverse cardiovascular events (MACEs) associated with BTK inhibitors." (PMID 40558238, 2025). "Importantly, none of the evaluated cotreatments were detected to increase the signal association to BTK inhibition over hypertension, according to the mechanistic models created." (PMID 40744952, 2025). "Hypertension is a recognized adverse effect associated with both ibrutinib and zanubrutinib, suggesting that hypertension may be a class effect of BTK inhibitors." (PMID 40346640, 2025). "Under conditions of BTKi treatment, the blockade of BTK results in the modulation of the NF-κB signal transduction cascade, potentially leading to the induction of immunosuppression, deterioration of vascular function, and exacerbation of hypertension and enhancement of cardiovascular risk." (PMID 40453665, 2025). "Additionally, BTKi, by inhibiting BTK activity, may cause an imbalance in the regulation of both the immune and vascular systems, contributing to hypertension." (PMID 40453665, 2025). "Although BTK inhibitors have revolutionized the treatment strategy for B-cell malignancies, induction of AF, hypertension, and ventricular arrhythmias has been demonstrated by BTK inhibitors in clinical use." (PMID 40346640, 2025). "Our in silico analysis showed that BTK inhibition seems to be unrelated to the molecular triggers of AF or hypertension." (PMID 40744952, 2025). "Among cardiovascular AEs of clinical interest to BTK inhibitors, rates of hypertension were 5.0% for acalabrutinib and orelabrutinib, 5.8% for ibrutinib, and 9.9% for zanubrutinib." (PMID 39271521, 2025). "Despite this, research and clinical data on hypertension induced by BTK inhibitors (BTKis) remain limited." (PMID 40453665, 2025). "A potential mechanism for BTKi-induced hypertension is that the inhibition of BTK leads to a decrease in p-PI3K and p-Akt levels, reducing eNOS activation and suppressing NO synthesis." (PMID 40453665, 2025). "Should patients develop hypertension during treatment with BTK inhibitors, clinicians are advised to intervene promptly in accordance with established guidelines for antihypertensive medications, such as ACEIs and ARBs." (PMID 40346640, 2025). "While CVSEs with second generation BTK inhibitors are less, 2-9% continue to experience arrhythmias, while comparable rates of hypertension between BTK inhibitors suggest a class effect." (PMID 38829647, 2024). "Unlike most AEs, which have the highest onset in the first year of BTK inhibitor therapy, the incidence of new onset hypertension increases over the course of treatment." (PMID 37185435, 2023). "The observation of increased hypertension with acalabrutinib adds to a growing body of evidence linking BTK inhibition with blood pressure modulation." (PMID 35836241, 2022). "In BTKi treatment, inhibition of BTK may downregulate Notch, disrupting vascular homeostasis, increasing vascular resistance, and accelerating the development of hypertension in patients undergoing BTKi therapy." (PMID 40453665, 2025). "Hypertension is a common AE observed in patients treated with BTK inhibitors." (PMID 37845755, 2023). "About 20% of patients on BTK inhibitor therapy will experience new or worsening hypertension." (PMID 37185435, 2023).
Hypertension (continued). "However, increasingly accelerated hypertension has been noted to contribute to the unanticipated higher burden of cardiovascular events among patients treated with BTK inhibitors and other anticancer therapies." (PMID 35836241, 2022). "In addition, two other pathways, the Notch and RhoA/ROCK signaling pathways, which regulate endothelial proliferation and vascular tone, have shown potential links to the BTK pathway and may contribute to the hypertension induced by BTKis." (PMID 40453665, 2025). "Each patient treated with BTK inhibitors, including ibrutinib, in Saskatchewan undergoes a detailed medical history review and a focused CV risk examination, including an electrocardiogram (ECG) and blood pressure measurement, to identify common risk factors such as AF and hypertension." (PMID 40558238, 2025). "The precise mechanism by which BTK inhibitors induce hypertension remains unclear." (PMID 40346640, 2025). "The mechanism(s) underlying ibrutinib-induced hypertension is unknown but is likely related to endothelial dysfunction, where the inhibition of BTK has been shown to interfere with nitric oxide synthesis, leading to increased vascular resistance and hypertension." (PMID 39685948, 2024). "BTK inhibitors are not recommended for patients with history of ventricular arrhythmia, family history of sudden cardiac death, severe uncontrolled hypertension, or severe or uncontrolled congestive heart failure." (PMID 38829647, 2024). "The key kinase of the BCR signal transduction pathway, BTK, is reversibly or irreversibly occupied by the binding of BTKi at the Cys481 residue and induces the alteration of the downstream PI3K/Akt, MAPK, and NF-κB pathways, potentially leading to the development of hypertension." (PMID 40453665, 2025). "TPMS modeling analysis suggested a lack of role for BTK inhibition in triggering hypertension." (PMID 40744952, 2025). "Additionally, BTK inhibitors are not recommended in individuals with ventricular arrhythmia, uncontrolled hypertension, or crisis." (PMID 40346640, 2025).
fungal infections (21 papers, 2016 to 2025). "The use of ibrutinib, a Bruton tyrosine kinase inhibitor, has been associated with invasive fungal infections (IFIs)." (PMID 38545450, 2024). "Bruton’s tyrosine kinase (BTK) inhibitors are associated with higher rate of infections, including invasive fungal infections." (PMID 37046650, 2023). "was regained after the recent report of an association between invasive fungal infections, including cryptococcosis, and ibrutinib, an irreversible inhibitor of Bruton's tyrosine kinase (BTK)." (PMID 35425769, 2022). "On the other hand, CLL and MCL patients treated with BTK inhibitors exhibit increased risk of invasive fungal infection, bacterial infection and hepatitis B reactivation." (PMID 34778053, 2021). "Overall, our work provides mechanistic and translational insights into how BTK orchestrates neutrophil-dependent defense during fungal infection, thereby illuminating the mechanisms underlying increased susceptibility to fungal disease of patients who have been treated with BTKi." (PMID 38696257, 2024). "Furthermore, BTK inhibition has been associated with impaired neutrophil effector activity against Cryptococcus neoformans and Aspergillus fumigatus, considered to increase the risk of invasive fungal infections." (PMID 39518015, 2024). "Perhaps these cells compensate for the decreased TNF-α produced by neutrophils during treatment with BTK inhibitors, resulting in less established fungal infections in the periphery." (PMID 38713531, 2024). "Given the propensity of invasive fungal infections in patients treated with BTK inhibitors, we examined opportunities to bypass BTK inhibition and restore neutrophil effector functions." (PMID 38713531, 2024). "Herein, we uncover the crucial role of BTK-dependent neutrophil activation in defense against systemic fungal infection." (PMID 38696257, 2024). "Bruton tyrosine kinase inhibitors (BTK), acalabrutinib, ibrutinib, and zanubrutinib, have been associated with increased risk for invasive fungal infections." (PMID 36836350, 2023). "Activation of BTK pathways in macrophages plays a significant role in the defense against fungal infection through phagocytosis and immune regulation." (PMID 36183125, 2022). "Here, we discussed the involvement of BTK signaling and the therapeutic potential of BTKi in viral, bacterial, and fungal infections." (PMID 36183125, 2022). "BTK inhibitors, such as ibrutinib, represent a key example where serious fungal infections were observed frequently outside of the clinical trial setting." (PMID 34947040, 2021). "Despite improved outcomes, rare adverse events, such as invasive fungal infections, have been reported with the use of first-generation BTK inhibitors." (PMID 33567487, 2021). "To decipher the importance of BTK in NLC during a fungal infection, we inspected the effect of acalabrutinib, a more specific BTK inhibitor." (PMID 32983178, 2020). "Our study aimed to understand the impact of BTK inhibition on immune response to fungal infection mediated by macrophages and CD14+ monocytic population obtained from CLL patients." (PMID 32983178, 2020). "BTK inhibitors are associated with bacterial respiratory infections and opportunistic infections like Pneumocystis jirovecii pneumonia (PJP) and invasive fungal infections, due to BTK inhibition impairing immune cell signaling." (PMID 40647394, 2025). "Indeed, studies have shown that BTK inhibition can impair innate responses against fungal infections in CLL patients." (PMID 39518015, 2024). "It is reported that myelosuppression and fungal infections might occur during antitumor therapy of BTK inhibitors, therefore a combination therapy with triazole antifungals is usually required." (PMID 36299883, 2022). "In addition to inflammatory diseases, bacterial and fungal infections, BTK plays a critical role in initiating antiviral responses." (PMID 33818636, 2021).
fungal infections (continued). "Inhibiting the BTK pathway suggests that it could lead to impairment in the adaptive and innate immune systems with fungal infection." (PMID 32333154, 2020). "Altogether, these results reported for the first time the biological effects induced in the monocytic population of CLL patients during treatment with ibrutinib, highlighting how inhibition of BTK affects its inflammatory profile that may compromise response to fungi infection." (PMID 32983178, 2020). "While these results are encouraging, the use of TNF-α during fungal infections in patients treated with a BTK inhibitor is not feasible, given the numerous off-target effects and induction of severe endotoxic shock." (PMID 38713531, 2024).
hepatocellular carcinoma (21 papers, 2013 to 2025). A malignant tumor that arises from hepatocytes. "In conclusion, regular IVIG infusions and adequate prophylactics prevented recurrent sinopulmonary infections in Taiwanese patients with BTK mutations except two who died due to hepatocellular carcinoma and pseudomonas sepsis before IgG infusion in 2004." (PMID 33013854, 2020). "Bruton’s tyrosine kinase (BTK) is a member of the tyrosine kinase expressed in hepatocellular carcinoma (TEC) family, and as a key kinase in the B cell receptor pathway." (PMID 41376625, 2025). "As a BTKi, in addition to inhibiting BTK, ibrutinib can inhibit several other intracellular molecules important for platelet signalling, including tyrosine kinase expressed in hepatocellular carcinoma (Tec)." (PMID 36678594, 2023). "Bruton’s tyrosine kinases (BTK) are cytoplasmic proteins belonging to the family of tyrosine kinases expressed in hepatocellular carcinoma (TEC) kinases." (PMID 35890078, 2022). "Bruton’s tyrosine kinase (BTK) is a cytoplasmic protein belonging to the family of TEC (tyrosine kinase expressed in hepatocellular carcinoma) kinases." (PMID 34150760, 2021). "Tec family includes five members: (I) tyrosine kinase expressed in hepatocellular carcinoma (TEC), (II) interleukin-2-inducible T cell kinase (ITK), (III) resting lymphocyte kinase (RLK), (IV) bone marrow expressed kinase (BMX), and (V) BTK." (PMID 38125430, 2023). "They include TEC (tyrosine kinase expressed in hepatocellular carcinoma), BTK (Bruton’s tyrosine kinase), ITK (IL2-inducible T-cell kinase), RLK (Resting lymphocyte kinase), and BMX (bone marrow-expressed kinase)." (PMID 34072040, 2021). "Bruton’s tyrosine kinase (BTK) belongs to the family of non-receptor tyrosine kinases (nRTKs) in hepatocellular carcinoma and was initially recognized to play a key role in the development and function of B cells." (PMID 37630287, 2023). "Bruton’s tyrosine kinase (BTK) is a non-receptor intracellular kinase that belongs to the Tec (tyrosine kinase expressed in hepatocellular carcinoma) family." (PMID 33818636, 2021). "In recent years, Bruton’s tyrosine kinase (BTK), a member of the TEC (tyrosine kinase expressed in hepatocellular carcinoma) family of non-receptor tyrosine kinases (NRTKs), has emerged as a key target in the suppressive phenotypes of MDSCs and TAMs." (PMID 40725182, 2025). "Bruton tyrosine kinase (BTK) is a cytoplasmic, nonreceptor tyrosine kinase from the tyrosine kinase expressed in hepatocellular carcinoma (TEC) kinase family that is primarily expressed in hematopoietic cells, particularly in B lymphocytes, but not in T cells or plasma cells." (PMID 36900295, 2023).
prostate carcinoma (20 papers, 2018 to 2025). A carcinoma that arises from epithelial cells of the prostate gland. "In particular, the 80 kDa isoform has been reported in breast and prostate carcinomas, whereas BTK-p65 has been shown to be abundantly expressed in colon and ovarian carcinomas, glioblastomas and NSCLC." (PMID 36612306, 2023). "In contrast, in cancer cells derived from solid tumors used in this analysis (HNSCC and prostate carcinoma), only BTK-p80/p65 mRNA was detectable, albeit at different expression levels." (PMID 36612306, 2023). "In this study, the authors discovered a strong expression of BTK detected in the prostate cancer tissues, especially in the tissue samples of tumors sampled from prostate cancer patients with bone metastases." (PMID 35456016, 2022). "Inhibition of BTK and ETK with a small molecule inhibitor caused inhibition of proliferation, clonogenic growth, invasiveness of human prostate cancer cell lines both in in vitro and an in vivo SCID mouse xenograft model." (PMID 33937249, 2021). "BTK inhibition was also associated with substantial downregulation of oncogenic genes, such as MYC, in prostate cancer cell lines and enhances their chemosensitivity to standard drugs such as docetaxel." (PMID 33937249, 2021). "The expression of BTK was correlated with prostate cancer grade in patient specimens and BTK promoted cell growth in vitro." (PMID 34307353, 2021). "Both BTK and the related TEC kinases ETK and BMX are abundantly expressed in prostate cancer cells, and knockdown of BTK expression in prostate cancer cells results in reduced proliferative activity." (PMID 33937249, 2021). "In prostate cancer, BTK was found to be overexpressed in prostate cancer tissues and prostate cancer cells." (PMID 34307353, 2021). "As with other adenocarcinomas, BTK expression has also been described in prostate cancer cells, with the BTK-C isoform predominantly expressed." (PMID 29561760, 2018). "In addition, we isolated TILs from localized and metastatic prostate cancers to perform immunofluorescence and further prove different BTK phosphorylation and the well-known immunosuppressive molecule PD-1 expression in B cells." (PMID 37190284, 2023). "Thus, isoform specific primers were used for quantitative RT-PCR of ten human HNSCC-derived cell lines and three prostate carcinoma cell lines, the latter serving as internal controls for oncogenic BTK expression." (PMID 36612306, 2023). "Notably, in prostate cancer cells, reducing the expression of BTK-C by RNAi or inhibiting its activity using BTK-specific inhibitors such as ibrutinib, AVL-292, or CGI-1746 leads to a decrease in cell survival." (PMID 36903645, 2023). "In addition, strong expression of BTK was detected in prostate cancer tissues, especially in tumors from prostate cancer patients with bone metastasis." (PMID 34164404, 2021). "The same group successively confirmed a survival role for BTK-C also in prostate cancer cells where its downregulation by RNAi or inhibition with BTK inhibitors induced apoptosis via induction of several apoptosis-related gene, as assessed by microarray analysis." (PMID 34164404, 2021). "Furthermore, the study in prostate cancer cohort indicated that BTK knockdown selectively inhibited the growth of prostate cancer cells." (PMID 32984343, 2020). "This is consistent with studies that show BTK signaling is important for adhesion and migration of B-cells and suggest that BTK-C may confer similar properties in prostate cancer cells to those in mature B-cells." (PMID 29561760, 2018). "Further, we tested several BTK/BMX inhibitors, with HPLC analyses showing that zanubrutinib or ibrutinib treatment significantly decreased DHEA metabolism in multiple prostate cancer (LNCaP, C4-2, and VCaP) cell lines." (PMID 36647826, 2023). "These compounds inhibited PKC-α, ROCK II and BTK with IC50 values ranging from 0.17 to 3.24 μM, and had cytotoxic activity in vitro against PC3 human prostate cancer cells." (PMID 31450856, 2019).
prostate carcinoma (continued). "It has also been shown that the inhibition of BTK expression by LFM-A13 decreased the proliferation of prostate cancer cells, but not normal prostate epithelial cells, which are characterised by low BTK expression." (PMID 32912025, 2020). "It has also been shown that the inhibition of BTK expression by LFM-A13 decreased the proliferation of prostate cancer cells, but not of normal prostate epithelial cells, which express very little BTK." (PMID 29690619, 2018). "In prostate cancer cell lines, down regulation of this protein with RNA interference or inhibition with BTKi, ibrutinib, spebrutinib and CGI-1746, all decreased cell survival and induced apoptosis via an on-target BTK mediated effect." (PMID 29561760, 2018). "However, a growing body of experimental and clinical data has demonstrated the significance of BTK, not just in B-cell malignancies, but also in solid tumors, such as breast, ovarian, colorectal, and prostate cancers." (PMID 36903645, 2023).